ADAMTSL5 (ADAMTS like 5)
Diseases named in the same sentence as ADAMTSL5 in open-access papers (continued):
Sharing a sentence is not in itself a finding about the gene and the disease.
melanoma (2 papers, 2024 to 2025). A malignant, usually aggressive tumor composed of atypical, neoplastic melanocytes. "Quantitative PCR analysis revealed that neither IFN-γ nor UVB radiation had a significant impact on mRNA transcript levels of the melanocyte autoantigen, ADAMTSL5, in PHMs or melanoma cell lines." (PMID 40243413, 2025). "ADAMTSL5 staining was also observed in melanoma skin metastasis of patient 2, with an intense and granular positivity in the cytoplasm." (PMID 38495872, 2024). "ADAMTSL5 also accumulated in melanophages/macrophages infiltrating tumoral and peritumoral areas, indicating that ADAMTSL5 protein is produced by melanoma cells in significant amounts and undergoes subsequent uptake by melanophages." (PMID 38495872, 2024). "ADAMTSL5 was expressed in most melanoma cells of primary tumor, with different intensity of staining." (PMID 38495872, 2024). "Finally, for patient 2, we performed ADAMTSL5 immunohistochemistry on skin specimens obtained from lesional, perilesional and 3-cm distant areas of the primary melanoma, from melanoma skin metastasis and anti-PD-1-induced vitiligo." (PMID 38495872, 2024). "It would be interesting to examine whether ADAMTSL5 might represent a potential antigen also for melanoma and other malignancies, recognized by CD8+ T cells with specific TCR repertoire." (PMID 38495872, 2024). "Besides melanoma, ADAMTSL5-specific immune responses could also be induced in other cancer types, being ADAMTSL5 dysregulated in a wide variety of malignant tumors, including lung cancer and hepatocarcinoma." (PMID 38495872, 2024).
vitiligo (2 papers, 2021 to 2024). Generalized well circumscribed patches of leukoderma that are generally distributed over symmetric body locations and is due to autoimmune destruction of melanocytes. "Finally, in vitiligo specimens of patient 2, ADAMTSL5 expression was absent in both perilesional and lesional skin, except for few cells infiltrating the dermis." (PMID 38495872, 2024).
gastric cancer (1 paper, 2022). A primary or metastatic malignant neoplasm involving the stomach. "We first demonstrated that ADAMTSL5 is downregulated in gastric cancer and plays an anticancer role." (PMID 35587154, 2022).
hepatocellular carcinoma (1 paper, 2021). A malignant tumor that arises from hepatocytes. "Changes in expression levels of ADAMTSL3 and ADAMTSL5 were reported in hepatocellular carcinoma, however opposite roles were suggested." (PMID 33805340, 2021).
liver cancer (1 paper, 2023). An epithelial or non-epithelial malignant neoplasm that arises from the liver. "Notably, Arechederra M and co-authors have provided evidence showcasing the pivotal role of ADAMTSL5, a protein synthesized by liver cancer cells, in the formation of tumors." (PMID 37502362, 2023).
plaque psoriasis (1 paper, 2024). "However, ADAMTSL5 was not detectable in all patients affected by plaque psoriasis, confirming that different (auto)antigens can elicit adaptive immune responses in the disease." (PMID 38495872, 2024).
tumor (4 papers, 2018 to 2024). "Conversely, in the area 3-cm distant from the margin of tumor, ADAMTSL5 positivity was only found in melanocytes." (PMID 38495872, 2024). "We then evaluated the expression of circPFKP, miR-644, and ADAMTSL5 in the tumor tissues." (PMID 35587154, 2022). "By contrast ADAMTSL5 expression was increased in tumor versus adjacent non tumor tissues." (PMID 33805340, 2021). "Importantly, ADAMTSL5 confers tumorigenicity by upregulating oncogenic inputs (i.e., MET, EGFR, PDGFRβ, IGF1Rβ, FGFR4), and its abrogation increases sensitivity of tumor cells to clinically relevant drugs." (PMID 38495872, 2024).
cancer (3 papers, 2021 to 2024). A tumor composed of atypical neoplastic, often pleomorphic cells that invade other tissues. "However, the effect of ADAMTSL5 on cancer progression has not been reported." (PMID 35587154, 2022).
ADAMTSL5 also shares sentences with these, for which no sentence is quoted: psoriatic arthritis (2 papers); autoimmune disease (1); infection (1); lung carcinoma (1); metastasis (1); renal cell carcinoma (1).